OR5M8 (olfactory receptor family 5 subfamily M member 8)
Description:
Odorant receptor.
Synonyms: OR11-194
Tractability: Antibody: UniProt places it where antibodies can reach, with medium confidence; UniProt predicts a signal peptide or a membrane-spanning region; its Gene Ontology location is reachable by antibodies, with medium confidence.
Gene: Protein-coding gene on chromosome 11 (56,490,435 to 56,491,370, reverse strand). Ensembl gene ENSG00000181371.
Subcellular location: Cell membrane
Pathways (Reactome):
Sensory Perception: Expression and translocation of olfactory receptors
Gene Ontology:
Molecular function: olfactory receptor activity; G protein-coupled receptor activity
Biological process: G protein-coupled receptor signaling pathway; sensory perception of smell; detection of chemical stimulus involved in sensory perception of smell
Cellular component: plasma membrane; membrane
Genetic constraint (gnomAD): Missense variants: 396 observed, 347.37 expected, observed/expected ratio (o/e) 1.14, 90% interval 1.05 to 1.24. Synonymous variants: 144 observed, 127.69 expected, observed/expected ratio (o/e) 1.13, 90% interval 0.98 to 1.29.
Homologues: Orthologues: chimpanzee OR5M8 (97% identical), dog OR5M8 (87% identical), mouse Or5m8 (85% identical), rat Or5m8 (84% identical), guinea pig OR5M8 (76% identical). Paralogues in human: OR5M3 (69% identical), OR5M9 (66% identical), OR5M10 (63% identical), OR5M1 (63% identical), OR5M11 (58% identical), OR8U1 (52% identical), OR5AP2 (52% identical), OR5B12 (52% identical), OR8U3 (52% identical), OR5L1 (51% identical), OR8A1 (51% identical), OR8D4 (51% identical), and 84 more.
Diseases named in the same sentence as OR5M8 in open-access papers:
OR5M8 is named in the same sentence as 1 disease in open-access papers, as found by Europe PMC text mining. Sharing a sentence is not in itself a finding about the gene and the disease.
OR5M8 shares sentences with these, for which no sentence is quoted: tumour (1 paper).